HIF1A (hypoxia inducible factor 1 subunit alpha)
Diseases named in the same sentence as HIF1A in open-access papers (continued):
Sharing a sentence is not in itself a finding about the gene and the disease.
infection (continued). "HIF-1α knockout mice showed a limited glycolytic activity in myeloid cells, coupled with a limited TNF-α production, arguing for a prominent role of HIF-1α during infection." (PMID 31708919, 2019). "Our studies revealed that orthologs of Hypoxia inducible factor 1α (HIF1α) and Lactate dehydrogenase (LDH) are required for macrophage activation, their bactericidal function, and resistance to infection, thus documenting the conservation of this cellular response between insects and mammals." (PMID 31609200, 2019). "Amplified HIF-1α caused upregulation of GLUT-1 and PDK1 in controls that was not further enhanced by infection." (PMID 31036602, 2019). "Both hydroxylase inhibitors increased il-1β:GFP in the absence of infection to a similar extent as that observed with DA Hif-1α." (PMID 30552162, 2019). "By stabilizing Hif-1α, macrophage Il-1β can be primed in the absence of infection and is protective upon M. marinum infection via neutrophil NO production." (PMID 30552162, 2019). "PD146176 also did not affect tnfa:GFP expression after Mm infection, nor did it block the protective effect of DA Hif-1α." (PMID 31611882, 2019). "Since the absence of HIF-1α is detrimental to host control of infection, we asked if large amounts of HIF-1α protein, exceeding those induced by H. capsulatum, altered macrophage responses to this pathogen." (PMID 31036602, 2019). "While Hif-1α-induced tnfa was downregulated by cyclooxygenase inhibition, it was notable that the high level of tnfa expression after inflammation or infection was not affected by cyclooxygenase inhibition." (PMID 31611882, 2019). "Given the host-specific nature of human gammaherpesviruses, the role of HIF1α in pathogenesis is difficult to elucidate as they exhibit limited lytic replication in vitro, and there is no established small animal model of infection." (PMID 31809522, 2019). "Both time periods of 5% oxygen incubation were sufficient to increase levels of il-1β:GFP in the absence of infection to a similar extent to both hydroxylase inhibition and DA Hif-1α." (PMID 30552162, 2019). "The link between HIF-1α and IL-1β has been previously demonstrated in murine macrophages via inflammatory activation by succinate, in the absence of infection." (PMID 30552162, 2019). "The infection of PBMCs with KSHV was confirmed by immuno-staining for KSHV latent protein LANA and the induction of hypoxia was confirmed by western blot to detect HIF1α." (PMID 29746587, 2018). "Since VEGF-A is a known HIF-1α target and HIF-1α is present in L. amazonensis- and L. major-infected lesions in humans and in preclinical models, it is possible that HIF-1α plays a role in infection-induced proliferation of the endothelial cells." (PMID 29520262, 2018). "Infection of mouse macrophages in vitro with L. amazonensis and L. donovani triggers HIF-1α accumulation under normoxic conditions without requiring any additional inflammatory signals." (PMID 29520262, 2018). "To evaluate whether viral DNA integration is required for eliciting the HIF-1α pathway, we spinoculated Jurkat HRE-GFP cells with a high multiplicity of infection (MOI) of integrase-defective HIV-1 (HIV-1ΔIN)." (PMID 30206166, 2018). "Previous research has shown that HIF-1α enhance macrophage migration to the site of infection by increasing the expression of CXCR4 and decreasing CCR5 expression, which leads to macrophage retention in the area of infection." (PMID 29762526, 2018). "Effector genes including Hif1a (HIF-1α), Irf7 (IRF7), Gzmb (granzyme B) and Gzmc (granzyme C), together with Cd47 as a control, were significantly downregulated in Cd47−/−, less than in WT NK cells upon infection." (PMID 30643501, 2018). "Following infection with HIV-1, both the percentage of infected cells and the amount of p24 released into the cell culture supernatant at day 3 postinfection were significantly reduced in HIF-1α-silenced CD4+ T cells." (PMID 30206166, 2018).
infection (continued). "Infections were done with HIV-1ΔIN because this viral mutant is capable of inducing HIF-1α activity in infected cells but does not produce viral progeny." (PMID 30206166, 2018). "We observed that infection with H. pylori increased the percentage of cells in the G0/G1 phase in sh-Scr C2 AGS cells, while the percentage of cells in S phase increased in sh-HIF-1α C7 AGS cells." (PMID 28401064, 2017). "HIF-1α transcripts expression in parenchymal and other non-immune cells do not respond to infection." (PMID 28542591, 2017). "Acquisition of regulatory functions was not dependent on HIF-1α, since Hifflox/flox–CD11c-Cre- monocytes showed a similar infection rate to Cre+ cells." (PMID 28892492, 2017). "This is the first evidence that during the early phase of infection, MCs do not respond to short-term hypoxia (3 h) via HIF-1α." (PMID 28553287, 2017). "If anything, a tendency toward increased expression was observed 24 h post-infection by H. pylori, and this trend was similar for cells expressing or not HIF-1α." (PMID 28401064, 2017). "Beyond the HIF-1α-mediated arrest in G1/G0 phase following infection, the percentage of cells in G2/M phase decreased, suggesting that additional effects of H. pylori on the cell cycle occur in a manner independent of HIF-1α." (PMID 28401064, 2017). "During short-term hypoxia, reflecting an acute local infection, MCs do not adapt via stabilization of HIF-1α." (PMID 28553287, 2017). "Therefore, it is possible that A. phagocytophilum activates HIF-1α through PI3K to regulate simultaneously the carbohydrate metabolism and cytoskeleton organization to facilitate infection and multiplication in tick cells." (PMID 28229048, 2017). "Because Leishmania amastigotes survival in macrophages is not impaired in the absence of HIF-1α, this suggests that HIF-1α mainly increases the susceptibility to infection of transitional forms of monocytes/macrophages." (PMID 28892492, 2017). "For the activation of NF-κB, IkappaB kinases (IKK), especially IKK-β, are required for the phosphorylation-induced degradation of NF-κB inhibitors in response to infection and inflammation, and IKK-β is also essential for HIF-1α accumulation in macrophages during bacterial infection." (PMID 27148269, 2016). "HIF-1α expression in human 5637 cells is not significantly altered during UPEC CFT073 infection, but becomes upregulated upon AKB-4924 treatment." (PMID 25927232, 2015). "In the present study though, we show that the IRF-5-dependent inflammatory milieu induced by Leishmania during the first week of infection inhibits CD8+ T cell expansion and the development of SLECs by inducing HIF-1α in dendritic cells and consequently altering DC functions." (PMID 26046638, 2015). "This is in contrast to the requirement for HIF1α in killing of multiple gram-negative and –positive bacteria in epidermal wound models of infection." (PMID 25255025, 2014). "HIF-1α stabilization and VEGF expression were reduced by the infection of Tβ4 lentiviral shRNA." (PMID 25271630, 2014). "Infection by microorganisms is known to generate a host cell stress response and in vitro infection of human foreskin fibroblast (HFF) by Toxoplasma gondii provoked elevated levels of HIF-1α." (PMID 24112286, 2014). "HIF1α plays an important role in innate immunity and host defense as myeloid cells have HIF-dependency for adaptation to hypoxic and inflamed microenvironments that develop during infection." (PMID 25255025, 2014). "We have previously reported that stabilized Hif-1α signaling upregulated neutrophil nitrotyrosine levels in zebrafish embryos in the absence of infection." (PMID 24967596, 2014). "The HIF-1α protein levels were dramatically increased from 21 days after infection until 42 days after infection, also suggesting the hypoxia is not related VEGF induction in nurse cells." (PMID 24351861, 2013).
infection (continued). "Although, initial infection rate of LD in HIF-1α attenuated cells was not affected but intracellular growth of LD was significantly inhibited; while, over-expression of stabilized form of HIF-1α promoted intracellular growth of LD in host macrophage." (PMID 22701652, 2012). "A strong increase of HIF-1α was detected within 8 h of infection that remained increased even after 24 h of infection but expectedly no change in HIF-1β was detected." (PMID 22701652, 2012). "In all cases (untransfected, mutant and wild-HIF-1α transfected), a similar number of latex beads was detected within macrophages (data not shown) further supporting that cellular amount of HIF-1α had no influence on the initial infection rate of LD." (PMID 22701652, 2012). "Mechanistically, C. atrati and 4′HAP activated GSK3β, destabilized HIF-1α, and curtailed parasite fitness; pharmacologic GSK3β inhibition restored parasite growth, whereas HIF-1α depletion further reduced survival, highlighting the GSK3β/HIF-1α axis as a host pathway that constrains infection." (PMID 41509906, 2026). "We suggest that the metabolic response of the kidney cells to the infection in the absence of IL-1R exacerbates the depletion of oxygen in the infection foci and contributes to the creation of local hypoxia, which in turn activates HIF-1α." (PMID 40097388, 2025). "Our observation that gefitinib treatment did not alter the infection-induced accumulation of HIF1α suggests that HIF1α activation occurs independently of EGFR signaling, however, further experiments are required to understand the interplay, if any, between HIF1α, EGFR and Integrin α3β1." (PMID 38902255, 2024). "Interestingly, our results show that HMPV pre-infection did not impair the LPS-stimulated activation of NF-κB and HIF-1α, transcription factors that stimulate IL-1β mRNA synthesis in human cells." (PMID 37435074, 2023). "HIF-1α, NF-κB and STAT have been reported to be major players in inflammation and their interactions could regulate the immune-metabolic response of the host cells during infection." (PMID 37143674, 2023). "Curiously, HIF-1α levels were similar to noninfected animals at later stages of infection." (PMID 36417626, 2022). "In turn, HIF-1α activates the transcription of A2BR, thus expression and activation of A2BRs could be a negative feedback mechanism that allows the host to balance successful infection control with resolution of pulmonary inflammation." (PMID 36374941, 2022). "However, HK2 KO and HIF1A KO cells pretreated with TNFα fully restricted HCMV initiation of infection, indicating these factors are not necessary for TNFα’s anti-viral activity." (PMID 35834576, 2022). "Taken together, the stabilization of HIF-1α promotes pathogen clearance in mycobacterial infection by the remodeling of metabolic pathways in macrophages, and the effect of HIF-1α can be beneficial or detrimental to the host depending on the infection stages or immune cell activation states." (PMID 36505429, 2022). "Separately, our data show that cells lacking Hif1α are more permissive to infection, suggesting Hif1α may play a role in limiting the initiation of infection." (PMID 35834576, 2022). "Importantly, the increase in bacterial load did not result in increased HIF1α stabilization at 4 h post-infection." (PMID 35755850, 2022). "However, the infection with C. burnetii for 4 h resulted in transient stabilization of HIF1α, which was almost absent at 24 h post-infection." (PMID 35755850, 2022). "The reason why increasing infection rates, which most likely result in increased numbers of secreted effector proteins, did not result in increased HIF1α degradation, is currently unknown." (PMID 35755850, 2022). "Finally, HIF-1α was increased in negative post-infection samples compared to negative pre-infection samples (542 ± 1697.5 vs." (PMID 36482106, 2022).
infection (continued). "Likewise, the absence of HIF-1A in host lung response to Histoplasma capsulatum resulted in a significant decrease in mouse survival as early as 3 days post infection, thought to be a result of increased IL-10 production." (PMID 34066663, 2021). "In addition, HIF-1α KO mice infected with B. abortus exhibited reduced frequency of splenic CD80+ and NOS2+ inflammatory macrophages in comparison with HIF-1α WT during the early phase of the infection." (PMID 33989349, 2021). "However, HIF-1α can also be stabilized and activated under normoxic conditions in a variety of situations, including contact with inflammatory cytokines (TNF-α, IL-6 and VEGF), exposure to ROS, cyclic mechanical stretch in vitro or by MV in vivo and infection." (PMID 32353952, 2020). "Furthermore, HIF-1α transcription activity increases phagocytes cells survival and stimulates the expression of some important factors including VEGF as well as pro-inflammatory cytokines (TNF, IL-1 and IL-12) in the site of infection." (PMID 33139969, 2020). "In support of the link between fungal melanin and mTOR/HIF-1α signaling, infection of macrophages with melanin-coated live ΔrodA/pksP conidia restored both p-p70S6K and HIF-1α translocation to the nucleus to levels comparable with those obtained after infection with the Δku80 strain." (PMID 32385235, 2020). "We hypothesized that this may be a part of an increased proinflammatory profile in innate immune cells; therefore, we tested whether Hif-1α is upregulating a proinflammatory program in the absence of infection using the il-1β:GFP transgenic line." (PMID 30552162, 2019). "DA Hif-1α was not sufficient to reduce M. marinum infection levels when il-1β expression was blocked, suggesting that the il-1β response to M. marinum infection is critical to control infection." (PMID 30552162, 2019). "Of note, we have previously shown that suppressing this transient early Hif-1α signal does not affect the outcome of infection, and this observation was replicated in the study, indicating that this natural, early Hif-1α stabilization is not sufficient to control infection." (PMID 30552162, 2019). "We demonstrate that host-derived hypoxia signaling, mediated by the Hif-1α transcription factor, can prime macrophages with increased levels of Il-1β in the absence of infection, upregulating neutrophil antimicrobial NO production, leading to greater protection against infection." (PMID 30552162, 2019). "Stabilization of Hif-1α upregulates il-1β transcription in macrophages in the absence of infection." (PMID 30552162, 2019). "As we have previously observed, DA Hif-1α upregulated NO in the absence of infection (PVP), an effect that is dampened by introduction of the bacteria (M. marinum) through currently unknown mechanisms." (PMID 30552162, 2019). "Additionally, in 780-O cells, which only contain HIF-2α but not HIF-1α, infection with the wild-type EPEC E2348/69 strain, or the control EPEC strain ΔnleBE+vector exhibited similar glucose uptake abilities (p = 0.1364)." (PMID 30125331, 2018). "Although HIF-1α deficient mice are susceptible to M. tuberculosis infection, the pleiotropic phenotypes observed in HIF-1α deficient mice during infection makes it impossible to determine whether the lack of LDs contributes to this failure of host defense." (PMID 29370315, 2018). "Furthermore, by 3 days post-infection, Hig2-/- BMDM had a nearly 90% defect in the average number of LDs per cell compared to wildtype BMDM, nearly as complete a defect as that observed in Hif1a-/- BMDM." (PMID 29370315, 2018). "In this study, even though we could not always detect the GlcNAcylation of endogenous HIF-1α by infection of the wild-type EPEC strain, we always observed that NleB delivered by the wild-type strain enhanced HIF-1α transcriptional activity." (PMID 30125331, 2018). "Similarly, the total protein level of HIF-1α was also not significantly changed in A549 or THP-1 cells at any infection dosage." (PMID 28536432, 2017).
infection (continued). "The results showed that, after 72 hours of exposure to infection, the expression level of PHD2 total protein in the LentiV-shPHD2-4 group was significantly lower compared to the other groups, and the expression level of downstream HIF-1α protein was significantly increased (P<0.05)." (PMID 29069818, 2017). "Interestingly, however, Δggt H. pylori were still able to induce HIF-1α upon infection of cells (data not shown)." (PMID 28401064, 2017). "In conclusion, the results obtained in this study uncover a novel role for HIF-1α in response to H. pylori infection of gastric cells, serving to connect an initial early potentially survival response, downstream of PI3K/mTOR activation, to G1/G0 cell cycle arrest later on following infection." (PMID 28401064, 2017). "In the absence of infection, nitrosylation levels at 2 dpf were significantly higher after DA hif-1αb injection, compared to control and DN hif-1αb injected embryos, suggesting that DA hif-1α leukocytes are already in an activated state prior to infection." (PMID 24367256, 2013). "Following in vitro infection of our small airway epithelial cell lines, we observe a robust increase in HIF1α protein accumulation with no increase in HIF1α mRNA abundance implying that R. delemar infection might alter the stability or degradation of the protein." (PMID 38902255, 2024). "Furthermore, irrespective of infection, JQ-1 administration also induced HIF-1α TF activity." (PMID 37747932, 2023). "Furthermore, the need for HIF-1α expression to mediate both IFN-γ-mediated and IFN-γ-independent CD4 T cell control emphasizes the central role of HIF-1α in cell-intrinsic control of infection and indicates that these two pathways of macrophage activation converge on HIF-1α activation." (PMID 35877763, 2022). "However, antiretrovial therapy (ART) may not fully restore HIF-1α activity to baseline following infection." (PMID 36467738, 2022). "Prior bone phenotypes following osteoblast-lineage knockout of Hif1a have revealed relatively subtle phenotypes, which may not have been readily detected in these studies given the potentially overwhelming influence of infection in our model." (PMID 36204648, 2022). "To examine whether the Ms_Rv0580c regulates the HIF-1α and ER stress marker genes, we pre-treated the THP-1 macrophages with TPCK (NF-κB inhibitor), SP600125 (JNK inhibitor) and SB202190 (p38 inhibitor), separately, for 1 h before infection with Ms_Rv0580c and Ms_pNIT." (PMID 33535567, 2021). "The precise mechanism of HIF-1α mRNA suppression after infection remains unknown, however it is unlikely that HIF-1α down-regulation is a consequence of transcriptional shut-down, since HIF-2α levels remain unchanged in infected hypoxic and normoxic cells at 24 h post-infection." (PMID 32244697, 2020). "However, due to technical limitations, we could not provide direct evidence that endogenous HIF-1α was indeed GlcNAcylated by NleB after infection with the WT and nleB mutant." (PMID 30125331, 2018). "Moreover, HIF-1α mRNA expression is not induced during infection." (PMID 29222473, 2017). "Interestingly, HIF-1α stabilization and the consequent metabolic shift occur during normoxia in several physiological and pathological conditions, particularly in rapidly proliferating cells, or upon infection with several viral and non-viral pathogens." (PMID 25351724, 2015). "Surprisingly, we observed that the role of myeloid HIF1α is not to mediate innate effector cell A. fumigatus killing directly, but rather to induce and maintain a protective immune response that ensures proper effector cell recruitment and survival at the site of infection." (PMID 25255025, 2014). "Results presented here further suggest that the infecting Mtb strain differentially affects the expression of HIF‐1α and NLRP3 inflammasome activation network genes and contributes to differential outcomes of infection (i.e., progressive vs. nonprogressive)." (PMID 41287823, 2025).